LINC00635 (long independently transcribed non-coding RNA 635)
Gene: Long non-coding RNA gene on chromosome 3 (107,840,228 to 107,882,250, reverse strand). Ensembl gene ENSG00000241469.
Diseases named in the same sentence as LINC00635 in open-access papers:
LINC00635 is named in the same sentence as 2 diseases in open-access papers, as found by Europe PMC text mining. Sharing a sentence is not in itself a finding about the gene and the disease. The quoted sentences say what the papers report.
hepatocellular carcinoma (1 paper, 2025). A malignant tumor that arises from hepatocytes. "Increased expression of ENST00000457302.2 and LINC00635 in hepatocellular carcinoma (HCC) is associated with lymph node metastasis (LNM), TNM stage, and overall survival (OS)." (PMID 40703556, 2025).
lymph node metastasis (1 paper, 2025). "There is only one study on LINC00635 expression in HCC, and in that study, serum LINC00635 expression has been reported to be associated with lymph node metastasis, advanced stage, and worse OS." (PMID 39397388, 2025).